TNFSF9 (TNF superfamily member 9)
Description:
Cytokine that binds to TNFRSF9. Induces the proliferation of activated peripheral blood T-cells. May have a role in activation-induced cell death (AICD). May play a role in cognate interactions between T-cells and B-cells/macrophages.
Synonyms: 4-1BBL; 4-1BB-L; CD137L; TNLG5A
Tractability: Small molecule: it has a high-quality binding pocket. Antibody: its Gene Ontology location is reachable by antibodies, with high confidence; UniProt predicts a signal peptide or a membrane-spanning region. PROTAC: ubiquitination databases record sites on it.
Gene: Protein-coding gene on chromosome 19 (6,531,026 to 6,535,924, forward strand). Ensembl gene ENSG00000125657.
Subcellular location: Membrane
Subcellular location (Human Protein Atlas): Golgi apparatus
Pathways (Reactome):
Immune System: TNFs bind their physiological receptors
Gene Ontology:
Molecular function: protein binding; signaling receptor binding; tumor necrosis factor receptor superfamily binding; tumor necrosis factor receptor binding
Biological process: cell-cell signaling; positive regulation of activated T cell proliferation; positive regulation of cytotoxic T cell differentiation; regulation of apoptotic process; regulation of T cell proliferation; cell communication; immune response; signaling
Cellular component: plasma membrane; membrane
Genetic constraint (gnomAD): Loss-of-function variants: 11 observed, 8.92 expected, observed/expected ratio (o/e) 1.23, 90% interval 0.77 to 1.84. That is too few expected variants to judge how well the gene tolerates losing a copy. Missense variants: 361 observed, 314.2 expected, observed/expected ratio (o/e) 1.15, 90% interval 1.05 to 1.25. Synonymous variants: 195 observed, 164.07 expected, observed/expected ratio (o/e) 1.19, 90% interval 1.06 to 1.34.
Homologues: Orthologues: chimpanzee TNFSF9 (98% identical), macaque TNFSF9 (91% identical), pig TNFSF9 (59% identical), mouse Tnfsf9 (32% identical), rat Tnfsf9 (31% identical).
Diseases named in the same sentence as TNFSF9 in open-access papers:
TNFSF9 is named in the same sentence as 108 diseases in open-access papers, as found by Europe PMC text mining. Sharing a sentence is not in itself a finding about the gene and the disease. The quoted sentences say what the papers report.
pancreatic cancer (13 papers, 2021 to 2025). "TNFSF9 exerted oncogenic effects in pancreatic cancer prostate cancer and glioma which also positively correlate with M2 polarization of macrophages." (PMID 40830812, 2025). "It has been shown that TNFSF9 can promote metastasis of pancreatic cancer through Wnt/Snail signaling and macrophage M2 polarization." (PMID 38706901, 2024). "Meanwhile, TNFSF9 promotes the metastasis of pancreatic cancer by Wnt/Snail signaling and macrophages M2." (PMID 37333498, 2023). "Activation of Src/FAK/p-Akt/IL-1β signaling by TNFSF9 is shown to increase pancreatic cancer metastasis by modulating the M2 polarization of macrophages." (PMID 36359832, 2022). "A previous study have found that TNFSF9 is expressed on a variety of tumor cells, promoting pancreatic cancer metastasis through Wnt/Snail signaling and M2 polarization of macrophages." (PMID 36117156, 2022). "In recent years, many studies have found that TNFRSF9/TNFSF9 is involved in immune regulation of various tumors, including pancreatic cancer and hepatocellular carcinoma, but their specific role in tumor development has not been clarified." (PMID 35894206, 2022). "Correlations between TNFSF9 expression and clinicopathological features in pancreatic cancer patients." (PMID 34517345, 2021). "We also studied the effect of TNFSF9 on the polarization state of macrophages in the microenvironment of pancreatic cancer, the effect of polarization state of macrophages on the function of pancreatic cancer cells, and the molecular mechanism of action." (PMID 34517345, 2021). "Additionally, TNFSF9 can induce the M2 polarization of macrophages by activating the Wnt signaling in pancreatic cancer cells, thereby promoting the metastasis of PC." (PMID 38612764, 2024). "TNFSF9 is significantly up-regulated in pancreatic cancer (PC) and may promote the growth and metastasis of PC in vivo and in vitro through the Wnt/Snail signaling pathway." (PMID 38612764, 2024). "In addition, TNFSF9 can induce the M2 polarization of macrophages by activating the Wnt signal of pancreatic cancer cells to secrete cytokines, thereby promoting the metastasis of pancreatic cancer." (PMID 34517345, 2021). "In conclusion, TNFSF9 may promote the metastasis of pancreatic cancer by activating its downstream Wnt/Snail signal." (PMID 34517345, 2021). "In conclusion, we hypothesized that TNFSF9 may affect the occurrence and development of pancreatic cancer by regulating the release of cytokines in the microenvironment." (PMID 34517345, 2021). "And then, we co-cultured TNFSF9-knockdown pancreatic cancer cells with U937-derived macrophages and found that compared with the sh-NC group, the mRNA levels of M1-type markers (TNF-α and IL-8) in sh-TNFSF9-1 and sh -TNFSF9-2 groups were increased and the mRNA levels of IL-1β were decreased." (PMID 34517345, 2021). "The results indicated that TNFSF9 may promote pancreatic cancer cells to release IL-10 and TGF-β through Wnt signal to promote M2 polarization of macrophages." (PMID 34517345, 2021). "However, another report showed that the expression of TNFSF9 in pancreatic cancer, leukemia and lymphoma, gastric cancer, renal cancer, and colorectal cancer was higher than that in adjacent normal tissues, indicating that TNFSF9 acts as an oncogenic factor in these cancers." (PMID 36142828, 2022). "Therefore, we hypothesized that the high expression of TNFSF9 in PC cells could not only directly promote the metastasis of pancreatic cancer, but also promote the metastasis of PC by inducing M2 polarization of macrophages and releasing some cytokines." (PMID 34517345, 2021). "Furthermore, we added Wnt agonist to TNFSF9 knockdown pancreatic cancer cells, and found that compared with the sh-TNFSF9 + DMSO group, the expressions of Wnt, β-catenin and Snail were increased in the sh-TNFSF9 + Wnt agonist group (P < 0.05), while the expression of TNFSF9 was not different." (PMID 34517345, 2021).
pancreatic cancer (continued). "In addition, at the mRNA and protein levels, the expression of TNFSF9 in pancreatic cancer cells ASPC-1, PANC-1 and BXPC-3 was significantly higher than that of normal pancreatic epithelial cells HPDE6-C7 (P < 0.05), while the expression of COLO357 was not different from HPDE6-C7." (PMID 34517345, 2021). "It shown that TNFSF9 may promote the metastasis of pancreatic cancer by regulating the EMT process." (PMID 34517345, 2021). "According to reports, TNFSF9 regulated macrophage M2 polarization through the Src/FAK/p-AKT/IL-1β signaling pathway, thereby facilitating the worsening of pancreatic cancer." (PMID 40830812, 2025). "In summary, TNFSF9 promotes the release of IL-10 and TGF-β from pancreatic cancer cells by activating Wnt signaling, thereby promoting M2 polarization of macrophages." (PMID 34517345, 2021). "In this article, we further found that the M2 polarization of macrophages co-cultured with TNFSF9 knockdown pancreatic cancer cells was reduced, and this result was dependent on the activation of Wnt signaling by TNFSF9 to promote the release of IL-10 and TGF -β in pancreatic cancer cells." (PMID 34517345, 2021). "In addition, compared with the sh-TNFSF9 + DMSO group, the migration of pancreatic cancer cells in the sh-TNFSF9 + Wnt agonist group was significantly increased (P < 0.05)." (PMID 34517345, 2021). "In addition, TNFSF9 also regulates the release of cytokines IL-10 and transforming growth factor-β (TGF-β) in pancreatic cancer cells through Wnt signaling to induce the M2 polarization of macrophages and promote the migration of PC cells." (PMID 34517345, 2021).
glioma (9 papers, 2022 to 2025). A benign or malignant brain and spinal cord tumor that arises from glial cells (astrocytes, oligodendrocytes, ependymal cells). "Hypoxic conditions promote lactate accumulation in glioma cells via glycolysis, which is then taken up by macrophages, triggering M2 polarization via the MCT1/H3K18la/TNFSF9 axis, thereby significantly exacerbating the malignancy of glioma cells." (PMID 39867891, 2024). "In the field of glioma, research focusing on TNFSF9 is rare, and only a few studies ended up just at the stage of clinical data analysis." (PMID 35982954, 2022). "A recent study revealed that hypoxia fosters lactate accumulation in glioma cells, which is subsequently taken up by macrophages, leading to M2 polarization via the MCT-1/H3K18 lactylation/TNFSF9 signaling pathway, ultimately promoting glioma progression." (PMID 39662177, 2024). "Glioma prognosis was correlated to immune checkpoints LGALS9, PVR, TNFSF9 and ICOSLG." (PMID 40777122, 2025).
leukemia (9 papers, 2005 to 2022). A malignant (clonal) hematologic disorder, involving hematopoietic stem cells and characterized by the presence of primitive or atypical myeloid or lymphoid cells in the bone marrow and the blood. "In this study, we identified TNFSF9/4-1BBL as a HDACi target that can mediate anti-leukemia allogeneic leukocyte response." (PMID 19759901, 2009). "Furthermore, we confirmed the overexpressed PIK3R5, DGKQ and TNFSF9, which are crucial components of kinase pathways involved in leukemia and lymphoma, in manipulated Jurkat samples." (PMID 27681508, 2016).
autoimmune disease (8 papers, 2013 to 2025). A disorder resulting from loss of function or tissue destruction of an organ or multiple organs, arising from humoral or cellular immune responses of the individual to their own tissue constituents. "These cells also overexpressed TNFSF9 (CD137L), a receptor involved in T cell activation that has become a significant target in autoimmune disease therapy." (PMID 37063898, 2023).
breast carcinoma (8 papers, 2015 to 2025). "TNFSF9 among these genes has an agonistic effect on the development of various cancers and bone metastasis in breast cancer." (PMID 40830812, 2025). "Studies have reported that TNFRSF9 suppresses tumor progression in breast cancer and that TNFSF9 reverse signaling induces apoptosis in non-small cell lung cancer cells, suggesting a potential role in the antitumor activity of DiPRO1." (PMID 39009887, 2024). "Additionally, in breast cancer, TNFSF9 enhanced the migration of monocytes/macrophages while promoting osteoclast differentiation, thereby accelerating bone metastasis of breast cancer." (PMID 40830812, 2025). "In breast cancer, TNFSF9 is cross-linked with TNFRSF9, which promotes monocyte/macrophage migration to the tumor microenvironment and osteoclast generation by upregulation of FRA1 expression, thereby promoting breast cancer metastasis." (PMID 34517345, 2021). "In addition, TNFSF9 also promotes bone metastasis of breast cancer by promoting monocyte/macrophage migration and osteoclast differentiation." (PMID 34517345, 2021).
melanoma (8 papers, 2015 to 2025). A malignant, usually aggressive tumor composed of atypical, neoplastic melanocytes. "In contrast, the expression of TNFSF9 was marginally higher in TMBlow melanomas (p=0.06) and correlated negatively with the TMB (r=-0.146, p=0.013)." (PMID 36389735, 2022). "Additionally, B7-H2 (CD86) mRNA was found in macrophages, PDCD1 (PD-1) mRNA was present in T cells (as expected), and TNFRSF14 and TNFSF9 mRNAs were observed in both T and melanoma cells." (PMID 40647495, 2025).
hepatocellular carcinoma (7 papers, 2017 to 2025). A malignant tumor that arises from hepatocytes. "As one of the members of the TNF superfamily, TNFSF9 is lowly expressed in human hepatocellular carcinoma tissues." (PMID 36142828, 2022). "However, recent data suggest that TNFSF9 reduces the proliferation of hepatocellular carcinoma, small cell lung cancer, and colorectal cancer." (PMID 34517345, 2021). "SNP in tumor suppressor genes, such as TNFSF10 and TNFSF9, are identified with the pathogenesis of various cancers, such as ovarian cancer and hepatocellular carcinoma, but these polymorphic genes may be answerable for the development of BRCA." (PMID 31311202, 2019).
lung carcinoma (7 papers, 2017 to 2026). "In addition, TNFSF9 was widely expressed in lung cancer cell lines at mRNA level, while the protein level was generally low." (PMID 34517345, 2021). "However, low expression of TNFSF9 protein was still sufficient to induce T cells to produce Interferon-γ (IFN-γ), followed by increased expression of programmed death ligand 1 in lung cancer cells." (PMID 34517345, 2021).
gastric cancer (6 papers, 2012 to 2025). A primary or metastatic malignant neoplasm involving the stomach. "Nine human RNAs were significantly upregulated in EBV-infected compared to EBV negative gastric cancers: FCER2, MS4A1 (CD20), PLUNC, TNFSF9, TRAF1, CXCL11, IFITM1, PPARG, and FCRL3.." (PMID 22929309, 2012).
Ewing sarcoma (4 papers, 2015 to 2024). A small round cell tumor that lacks morphologic, immunohistochemical, and electron microscopic evidence of neuroectodermal differentiation. "Ewing sarcoma cDCs showed significantly lower percentages of CD83-, CD86-, and TNFSF9-expressing cells and Ewing sarcoma Mφ had significantly lower CD70-, CD80-, CD83-, and TNFSF9-expressing cells, than neuroblastoma." (PMID 37823774, 2023). "With regard to clinical relevance, MEF3-related genes TRAF1 and TNFSF9, as well as direct cis-targets of DiPRO1 (Dataset EV1A,B) that transcriptionally respond to DiPRO1 KD in RMS and Ewing sarcoma cells in vitro (Dataset EV3), were analyzed in biopsies of recurrent tumors." (PMID 39009887, 2024).
Stroke (4 papers, 2018 to 2025). Sudden impairment of blood flow to a part of the brain due to occlusion or rupture of an artery to the brain. "Transcriptional analysis confirmed a reduction in expression of co-stimulatory genes in the spleen known to be expressed by macrophages 1–5 days after experimental stroke including Cd40, Cd80, Cd86, Icam1, Tnfsf9, which encodes 4-1BBL, and Cd274." (PMID 29872438, 2018). "Specifically, PPARα KO led to increased expression levels of Gadd45b, Nppa, Hdc, Lcn2, Il6, Sox4, Marcksl1, Saa3, Ucn2, Met, Dusp10, Elovl7, Ngf, C3, Il11, Hmox1, Alox5, Tnfsf9, Angptl4, Plin2, H19, Csf2rb, Atf3, and Col7a1 following stroke." (PMID 40362325, 2025). "Female MMP-3 KO stroke brains showed downregulation of the macrophage classical activation signaling genes Tnf and Tnfsf9, and decreased expression of the acute phage response genes Tnfrsf1a, Jun, Tnfrsf1b, Il6, Tnf, and Fos." (PMID 39000490, 2024).
viral infection (4 papers, 2020 to 2024). "On the other hand, HCV-associated cNK cells showed a pro-inflammatory profile, with high expression of the chemoattractants CCL3, CCL4, and XCL1, and the ligand TNFSF9 (CD137L), a costimulatory signal that can induce CD8+ T cells response against viral infection." (PMID 37063898, 2023).
colon cancer (3 papers, 2022 to 2025). "In colon cancer patients, TNFSF9 expression is highly upregulated in tumor tissues, and is significantly correlated with the occurrence of distant metastases in advanced disease and the shortened survival." (PMID 36117156, 2022).
colorectal cancer (3 papers, 2013 to 2022). A primary or metastatic malignant neoplasm that affects the colon or rectum. "Although TNFSF9 inhibited the proliferation of colorectal cancer cells in colorectal cancer, TNFSF9 also promoted the occurrence of EMT in colorectal cancer cells." (PMID 34517345, 2021).
osteosarcoma (3 papers, 2017 to 2024). A usually aggressive malignant bone-forming mesenchymal neoplasm, predominantly affecting adolescents and young adults. "However, osteosarcoma patients in the low-risk group had a lower TNFSF9 expression, which was associated with immune response and cell growth in osteosarcoma." (PMID 37964984, 2023). "In the low TELscore group, TNFSF9 and CD24 were the most active signaling pathways of checkpoints in osteosarcoma cells." (PMID 39980969, 2024).
B-cell lymphomas (2 papers, 2015 to 2021). "TNFSF9 (CD137L, 4–1BBL) is involved in T-cell activation, but its expression is associated with B-cell lymphomas." (PMID 25710169, 2015).
brain tumor (2 papers, 2025 to 2026). "Thus, we show that ZIKV infection of brain tumour cells leads to the upregulated expression and secretion of key members of both TNF alpha and TNFSF9/TNFRSF9 signalling pathways." (PMID 40240536, 2025).
Burkitt lymphoma (2 papers, 2013 to 2025). A rare form of malignant mature B-cell non-Hodgkin lymphoma. "In addition, a recent study using array-CGH and SNP-chip analyses reported that recurrent deletions of the tumor suppressor genes, TNFSF7 and TNFSF9 at the 19p13.3 region were observed in DLBCL and Burkitt lymphomas." (PMID 24220305, 2013).
liver cancer (2 papers, 2022 to 2023). An epithelial or non-epithelial malignant neoplasm that arises from the liver. "The studies found that TNFSF9 facilitates antitumor immunity in liver cancer and inhibited the proliferation of small cell lung cancer cells and induced apoptosis." (PMID 35982954, 2022).
osteoporosis (2 papers, 2022 to 2024). A condition of reduced bone mass, with decreased cortical thickness and a decrease in the number and size of the trabeculae of cancellous bone (but normal chemical composition), resulting in increased fracture incidence. "After the non-SDEGs added by GeneMANIA to establish the PPI network removed, six up-regulated SDEGs (HIST1H3G, HIST1H2BO, PTP4A1, FAM46A, MT1G and TNFSF9) and one down-regulated SDEG (PMAIP1) were identified as potential hub genes in the pathogenesis of osteoporosis." (PMID 38372699, 2024).
type 1 diabetes (2 papers, 2019 to 2021). "The effect of the upregulation of Tnfsf9 is difficult to define, because TNFSF9, also known as CD37 ligand and 4-1BBL, has a cell context dependent role in (auto) immune regulation, including type I diabetes, and in immune system homeostasis." (PMID 31083422, 2019).
Cerebral ischemia (1 paper, 2025). Restriction of arterial blood supply to the brain associated with insufficient oxygenation to support the metabolic requirements of the tissue. "Additionally, TNFSF9 (tumor necrosis factor superfamily member 9) is upregulated in response to cerebral ischemia–reperfusion injury and can exacerbate inflammation and cell death by promoting ferroptosis and apoptosis in brain microvascular endothelial cells." (PMID 40362325, 2025).
cervical squamous cell carcinoma (1 paper, 2024). A squamous cell carcinoma arising from the cervical epithelium. "In cervical squamous cell carcinoma (CESC), ICOS, KIR2DL4, TNFSF9, and CD86 function in immune activation and display a negative association with METTL3 expression." (PMID 39199429, 2024).
COVID-19 (1 paper, 2024). A disease caused by infection with severe acute respiratory syndrome coronavirus 2. "COVID-19 can induce cytokine storms, such as IL6, IL32, CD83, CCL2, CXCL11, the TNF family (TNFSF9 and the receptor TNFRSF9), and integrin-related genes, which exacerbates COVID-19 related myocarditis and decreases the prognosis of patients requiring ECMO treatment." (PMID 39026189, 2024).
inflammatory bowel disease (1 paper, 2022). A spectrum of small and large bowel inflammatory diseases of unknown etiology. "In the ssGSEA of TNFSF9, 164 pathways were enriched, mainly enriched in Chemokine signaling pathway, IL−17 signaling pathway, Inflammatory bowel disease, and other pathways." (PMID 35982954, 2022).
Lymphatic Metastasis (1 paper, 2021). Transfer of a neoplasm from its primary site to lymph nodes or to distant parts of the body by way of the lymphatic system. "The expression of TNFSF9 is associated with lymphatic metastasis (P = 0.017) and TNM stage (P = 0.003)." (PMID 34517345, 2021).
metastatic disease (1 paper, 2024). "While PRAME is a driver for genomic instability and recognized as a strong predictor for metastasis for metastatic disease, the expression of TNFSF9 is significantly higher in PRAME positive GEP class 2 tumors." (PMID 38191418, 2024).